PVT1 (Pvt1 oncogene)
Diseases named in the same sentence as PVT1 in open-access papers (continued):
Sharing a sentence is not in itself a finding about the gene and the disease.
tumor (continued). "If the “promoter–enhancer competition” between PVT1 and MYC commonly exists in cells, the PVT1 promoter serves as a tumor suppressor, and will further downregulate the expression of MYC, preventing the development of MYC-driven tumors." (PMID 31309249, 2019). "Pvt1 likely promotes tumor progression by promoting proliferation and inhibiting apoptosis in most tumor cells." (PMID 30925926, 2019). "In tumor tissues, the major transcription product of the PVT1 gene, PVT1 (an lncRNA), increases the level of c-Myc by enhancing the stability of it via blocking the phosphorylation of the Thr58 site on c-Myc." (PMID 31309249, 2019). "The level of lncRNA Pvt1 in G-MDSCs from tumor tissues was clearly higher than that in G-MDSCs from spleens or bone marrow." (PMID 30925926, 2019). "Recently, antisense LNA GapmeRs have been used by researchers to degrade PVT1 in acute erythroleukemia cell lines, which can increase apoptosis and necrosis of tumor cells." (PMID 31309249, 2019). "The authors found PVT1 to be overexpressed in OS cell lines and in tumor samples compared with healthy tissue." (PMID 31781490, 2019). "Overall, mouse xenograft studies confirmed that PVT1 overexpression increased tumor volume and decreased overall survival while knocking down PVT1 had the opposite effect." (PMID 31249809, 2019). "In this review, we center on PVT1, a large and complex long non-coding RNA that usually confers oncogenic properties on different tumor types." (PMID 31781490, 2019). "In keeping with the Pvt1 findings, the c-myc level in G-MDSCs from tumor tissues was considerably higher than in the spleens and bone marrow from TB mice." (PMID 30925926, 2019). "Several other studies have indicated the complicated regulatory relationship between PVT1 and Myc in tumor initiation." (PMID 31497532, 2019). "Human PVT1 is overexpressed in HCC tumor tissues and cell lines and is linked with advanced TNM stage and poor prognosis as well as RFS, and upregulation of PVT1 can also predict HCC recurrence." (PMID 30105249, 2018). "Compared with corresponding adjacent non-tumor tissues, PVT1 was up-regulated in 85.45% (47 of 55) of CCRCC tissues according to qRT-PCR." (PMID 29254209, 2017). "Our data also showed that PVT1 was increased in CCRCC tissues versus the corresponding non-tumor tissues." (PMID 29254209, 2017). "PVT1, as a candidate oncogene, was revealed to be related with cell proliferation and tumor progression in many neoplastic diseases." (PMID 28389669, 2017). "In the same study, tumor progression following down-regulation of PVT1 in tumor xenografts in mice was shown to be increased." (PMID 28637507, 2017). "In an attempt to elucidate the roles and downstream events of PVT1 in ccRCC, we firstly evaluated the expression level and clinicopathologic significance of PVT1 via bioinformatic database and PCR validation with tumor samples and cell lines." (PMID 29156724, 2017). "Here, we showed that PVT1 expression is significantly up-regulated in ESCC tumor samples compared with their normal counterparts." (PMID 28404954, 2017). "We found that silencing PVT1 reduced xenograft tumor growth, which was partially rescued by Mcl-1 overexpression." (PMID 29254209, 2017). "On the contrary, PVT1 was significantly upregulated while miR-200s were downregulated in ccRCC tumor tissues, and this implies the possibility for PVT1 to bind miR-200s and act as a ceRNA in ccRCC." (PMID 29156724, 2017). "A dramatic increase in tumor volume and weight was observed in the PVT1 group compared with pCDH group, while sh-PVT1 group showed relatively significant decrease in tumor volume and weight." (PMID 29156724, 2017). "Although PVT1 locus harbors several miRNA genes, their expression levels were similar between tumor and normal tissues." (PMID 27366943, 2016).
tumor (continued). "In the same study, 3AO tumor xenografts in mice displayed an induced rate of growth upon PVT1 downregulation." (PMID 26992233, 2016). "Next, we explored the variability functions of PVT1 in the normal physiological conditions and tumor." (PMID 27580177, 2016). "The transcript levels of PVT1 were significantly up-regulated in 71.25% (57 of 80) cancerous tissues compared with adjacent non-tumor tissues (p < 0.01)." (PMID 25890171, 2015). "The median expression for PVT1 in tumor tissues was used to divide the samples into high (above the median, n = 40) and low (below the median, n = 40) PVT1 expression group." (PMID 25890171, 2015). "Overexpression of PVT1 transcript has been documented in a variety of tumor tissues and miR1206 expression has been found in increased levels in B cell tumors." (PMID 25793711, 2015). "Tumor 324 contained only a single integration at the Gfi1/Evi5 locus however it contained two integrations at the Myc/Pvt1 locus." (PMID 24886479, 2014). "On the other hand, a miRNA located 50 kb downstream of PVT1, hsa-mir-1208, showed an interesting pattern of expression and interaction between sample status (normal/tumour) and genotype of rs378854." (PMID 21814516, 2011). "LncRNA PVT1 potentially regulates tumor resistance through the induction of autophagy." (PMID 40191723, 2025). "Inhibition of PVT1 has been shown to reduce PD-L1 levels and enhance immune-mediated tumor killing, suggesting that targeting PVT1 could be a promising strategy for immunotherapy in BLBCs." (PMID 41011238, 2025). "Because the literature suggests full-length PVT1 suppresses type I interferon signaling in tumor models, we wanted to explore whether PVT1 exon 9 also elicits this phenotype." (PMID 40024473, 2025). "LncRNA PVT1 plays a regulatory role in gynaecological cancer and is involved in regulating many processes of cellular biology, such as the proliferation, migration, invasion and drug resistance of tumour cells." (PMID 38098223, 2024). "For instance, PVT1 could interact with EZH2 to guide PRC2 to suppress expression of genes associated with pro-apoptotic and tumor suppressor, to promote multiple myeloma progression." (PMID 39376555, 2024). "In summary, our findings indicate that PVT1 might affect tumor immune regulation via modulating the interferon type I receptor signaling pathway." (PMID 38287522, 2024). "In addition, it was observed that PVT1‐214 suppression leads to an increase in miR‐128 transcription levels in tumour cells." (PMID 38506091, 2024). "However, additional carefully designed GEMMs are needed to deconvolve the oncogenic and tumor-suppressive elements in the Pvt1 locus and to dissect the interplay between regulatory DNA and RNA elements." (PMID 39195572, 2024). "PVT1 is a tumor-specific gene located on human chromosome 8q24.21." (PMID 36869031, 2023). "Moreover, PVT1 inhibition promotes the infiltration of CD8+ T cells into the tumor microenvironment, thereby enhancing immunotherapy by PD1 blockade." (PMID 36894542, 2023). "Thus, we implied that PVT1 was not only functions as an important factor of the tumor proliferation but also results in the resistance of TMZ chemotherapy through regulating JAK/STAT pathway." (PMID 37202742, 2023). "The tumor growth of the sh-PVT1#3 group was slower than that of the control with sh-NC group." (PMID 36944636, 2023). "Our RNA-seq analysis showed that PVT1 may promote tumor development by changing metabolism of cells substance, especially glycolysis." (PMID 36941464, 2023).
tumor (continued). "Therefore, PVT1 knockdown also exhibited strong suppression of tumor proliferation and promotion of apoptosis in an animal model of cSCC, which was consistent with the in vitro results." (PMID 36944636, 2023). "PVT1’s normal expression is monoallelic, and as its promoter competes with the MYC promoter for intragenic PVT1 enhancers on its single expressed allele, in doing so, it acts as a tumor suppressor by regulating the release of MYC transcriptional pausing." (PMID 37444543, 2023). "We found lncRNA PVT1 was primarily enriched in the cytosol that might function in ceRNA mechanisms that sponge miR‐1258 to promote tumor invasion." (PMID 36524545, 2023). "To investigate whether the PVT1 KD affects tumor development in vivo, we used a lentivirus-based short-hairpin RNA (shPVT1) to knockdown PVT1 in HN6 cells." (PMID 36894542, 2023). "In addition, exosomal circ-PVT1 expression levels were elevated in GC tissues, and high expression of circ-PVT1 was positively correlated with tumor LNM grade, LNM, and tumor size." (PMID 38094607, 2023). "PVT1 inhibition could induce tumor immune response, indicating that in vivo ASO-mediated inhibition of PVT1 might potentiate PD1 blockade." (PMID 36894542, 2023). "Moreover, we revealed a novel molecular mechanism by which lncRNA PVT1 can connect with the 4EBP1 protein and regulate its expression, thus resulting in enhanced tumor progression of cSCC." (PMID 36944636, 2023). "proves that Pvt1 is highly expressed in tumour-expanding G-MDSCs." (PMID 36817434, 2023). "Moreover, the epithelial–mesenchymal transition plays a pivotal role in PVT1‐induced tumor development in prostate cancer cells." (PMID 36524545, 2023). "ALKBH5 may act as tumor suppressor in pancreatic cancer but on the contrary, as tumor promoter in osteosarcoma via upregulation of PVT1 lncRNA." (PMID 36969033, 2023). "Another study reported that PVT1 regulates miR-497 to promote tumor formation in patients with NPC." (PMID 36195846, 2022). "Lastly, small nucleolar RNA host gene 14 (SNHG14) and plasmacytoma variant translocation 1 (PVT1), two other lncRNAs that promote tumor aggressiveness and lower OS (p < 0.001 and p < 0.032), respectively, were reported to act by sponging, respectively, the miRNAs miR-124 and miR-488-3p." (PMID 35432447, 2022). "Therefore, PVT1 promotes tumor cell malignant biological behaviors including proliferation, migration, and invasion and inhibits cell apoptosis." (PMID 35664988, 2022). "As for PVT1, the corresponding lncRNA of MYC, although it was confirmed to be associated with a variety of malignancies and promote tumor cell proliferation, migration, tumor growth and metastasis, and adipogenic potential, the lipid metabolism of PVT1 regulating is still unclear." (PMID 35501901, 2022). "In other words, PVT1 promoted tumor cell migration and invasion ability." (PMID 35664988, 2022). "The increased expression of Pvt1 which is induced by HIF-1α under hypoxia causes the down-regulated expression of Arg-1 and ROS in PMN-MDSCs, and assists T cells to suppress tumor growth in tumor-bearing mice." (PMID 36569895, 2022). "The candidate oncogene PVT1 is also specifically gained in tumours with high SCS." (PMID 35326573, 2022). "We therefore tested if reducing PVT1 levels altered intraperitoneal tumor growth." (PMID 35820706, 2022). "PVT1 can also regulate tumor progression through the lncRNA–miRNA–mRNA axis in patients with GC." (PMID 36195846, 2022). "Therefore, it seems that while PVT1 RNAs have an oncogenic role, PVT1 gene regulatory DNA can have a tumor-suppressive role." (PMID 36052265, 2022). "As a mediator of tumor progression, PVT1 also has multiple regulatory mechanisms." (PMID 36295083, 2022). "In addition, another study pointed out that PVT1 promotes tumor growth by regulating miR-146a methylation." (PMID 36195846, 2022).
tumor (continued). "For example, lncRNA PVT1 which located in 8q24 region is activated by amplification in multiple tumor types, and PVT1 could participate in the regulation of tumorigenesis." (PMID 35371316, 2022). "The molecular mechanisms accounting for increased MYC and PVT1 expression in most tumor samples in our study are currently unknown, and this line of work will be addressed in future studies." (PMID 36139061, 2022). "Induction of PVT1 promotes tumor cell survival, growth, and migration." (PMID 35820706, 2022). "We found that the PVT1 locus was co-amplified in each of these tumor samples." (PMID 36139061, 2022). "In this study, we noted that Pvt1 was up-regulated in co-cultured MSCs, Pvt1 knockdown inhibited the proliferation and migration of co-cultured MSCs, indicating that Pvt1 exerts a promoting function in the tumor-like transformation of MSCs." (PMID 36295083, 2022). "Some of those have found that PVT1 was involved in the regulation of angiogenesis in tumor tissues." (PMID 35036445, 2022). "Interestingly, positive correlations between PVT1 overexpression and tumour progression are frequently observed (see the section “Clinical impact of lncPVT1 and circPVT1”)." (PMID 34754096, 2022). "Taken together, these results indicated that PVT1 depletion suppressed CC tumor growth in vivo." (PMID 33817293, 2021). "In conclusion, our findings suggest that the rs13255292 and rs2608053 SNPs in PVT1 may be associated with GC risk in certain GC subgroups characterized by LNM, tumor stage, and sex." (PMID 35049170, 2021). "Importantly, PVT1 itself was processed into several oncogenic or tumor suppressor miRNAs (including miR-1206, miR-1204, miR-1207-3p, miR-1207-5p, and miR-1208)." (PMID 34828307, 2021). "Interestingly, a set of androgen repressed genes increased their expression levels after PVT1 knockdown, and tumor suppressor genes were enriched among them." (PMID 33430890, 2021). "Additionally, PVT1 inhibition also decreased the tumour growth and the proportion of proliferating cells in a xenograft tumour‐bearing mouse model." (PMID 34288373, 2021). "Besides, a recent study indicated that lncRNA PVT1 was highly expressed in GC tissues and can promote tumor progression by interacting with FoxM1, and PVT1." (PMID 33464142, 2021). "Interestingly, the association with the tumor stage seemed to be highest in stage III, while in stages I, II, and IV, there were lower proportions of patients with a high level of PVT1." (PMID 33947142, 2021). "Then, the abnormally expressed PVT1 functioned as an oncogene in PCa, contributing to tumor growth." (PMID 33971627, 2021). "Therefore, by detecting the expression of lncRNA PVT1 in tumor tissue, we can have a comprehensive analysis and evaluation of the patient's condition and prognosis and provide a reference for the realization of individualized treatment." (PMID 34900027, 2021). "Previous studies have found that PVT1 can promote angiogenesis in tumor tissues." (PMID 34336125, 2021). "The interactions of PVT1 with some miRNAs can mediate its positive effect on tumor proliferation." (PMID 34322395, 2021). "Moreover, the report inferred both subtypes of MDSC (M-MDSC and G-MDSC) isolated from the tumor tissue showed an upregulated expression of PVT1 with increased Arg1 and ROS expression." (PMID 34303380, 2021). "PVT1, as a potential oncogene, can promote tumor proliferation." (PMID 34336125, 2021). "To determine whether miR-328-3p and/or miR-3127-5p are the target miRNAs of PVT1 for its regulation of tumor cell proliferation, we investigated the levels of miR-328-3p as well as miR-3127-5p in tissues of ccRCC and adjacent normal parts from 45 patients." (PMID 34518442, 2021).
tumor (continued). "Although the combination of MALAT1 and PVT1 with other tumor markers may improve the early CRC diagnosis, this needs further investigation." (PMID 34200314, 2021). "This may lie behind the known aggressive phenotype of tumors expressing high levels of PVT1 oncogene, which highlights the pathway towards further investigation of the mechanisms that link PVT1 and its tumor suppressor targeted genes." (PMID 33430890, 2021). "Moreover, PVT1 seems to be a precursor to other miRNAs with either oncogenic or tumor-suppressive effects." (PMID 33947142, 2021). "In addition, they demonstrated that patients with high lncRNA PVT1 expression have a poor prognosis and that the downregulation of lncRNA PVT1 expression can inhibit the invasion, migration, and proliferation of tumor cells." (PMID 32960485, 2021). "PVT1 or AGO1 inhibition is also responsible for the promoted Ki67 level in excised tumour tissue." (PMID 34288373, 2021). "Additionally, silencing of PVT1 in addition to miR-190a-5p and miR-488-3p mimics prolonged survival and reduced tumor volume in mice with tumor xenograft." (PMID 34322395, 2021). "Besides, associations between these lncRNAs and CRC clinicopathological parameters were found, such as stage, nodal and distant metastases, suggesting that MALAT1 and PVT1 play a crucial role in directly contributing to tumor progression." (PMID 34200314, 2021). "Finally, we explored the possible regulatory mechanism of PVT1 and observed that miR-152-3p, a tumor suppressor, contains binding sites at the 3′-UTR of PVT1 and VEGFA." (PMID 34336125, 2021). "Finally, the study confirmed that MKL1 can reverse-activate the transcription of PVT1 and MKL1 and PVT1 formed a positive feedback loop that contributed to tumor migration." (PMID 32156248, 2021). "In addition to epigenetic silencing of LATS2, PVT1 also acts as a ceRNA for tumor suppressor miRNAs miR-200a and miR-200b to increase their target MMP-9, which promoted the invasive ability of NSCLC cells." (PMID 32629922, 2020). "Moreover, PVT1 expression also contributed to the increased level of Ki67 in xenograft tumor tissues." (PMID 32727463, 2020). "Moreover, 55 GBC patients were divided into two groups according to the median ratio of the relative PVT1 expression in tumor tissues: the high group (n = 30, fold change ≥ mean ratio) and the low group (n = 25, fold change < mean ratio)." (PMID 33067424, 2020). "Patients #9 and #10 both had a HER2‐negative tumour component with a gain of 8q24, which comprised a copy number gain of both MYC and the adjacent long noncoding RNA (lncRNA) plasmacytoma variant translocation 1 (PVT1)." (PMID 32058674, 2020). "PVT1, as a ceRNA, competes with endogenous miR-20a-5p to increase the expression of ULK1 protein, which is upregulated in a variety of tumor types and associated with tumor progression and chemoresistance." (PMID 32042268, 2020). "The high expression of PVT1 was also found in both ccRCC cell lines and clinical tumor tissues." (PMID 32226492, 2020). "Tumor xenografts experiments revealed that PVT1 level correlated with miR-519d-3p and HIF-1A level." (PMID 32201527, 2020). "PVT1 produces a wide variety of spliced non-coding RNAs, as well as a cluster of six annotated microRNAs: miR-1204, miR-1205, miR-1206, miR-1207-5p, miR-1207-3p, and miR-1208, which can promote tumor proliferation, and the resistance of chemotherapy." (PMID 33076512, 2020). "Finally, validation of miRNA18a/HIF1A/PVT1 pathway was checked via reverse transcription-polymerase chain reaction (RT-PCR) assay in both cell lines and clinical tumor samples." (PMID 32226492, 2020). "PVT1 functions as a tumor promoter in NSCLC via sequestering miR-526b to modulate EZH2." (PMID 33088221, 2020). "Collectively, our findings suggested that PVT1 could act as an oncogenic lncRNA, and promote tumor progression by regulating HIF-1A via competing with miR-519d-3p." (PMID 32201527, 2020).